ERBB3 (erb-b2 receptor tyrosine kinase 3)
Diseases named in the same sentence as ERBB3 in open-access papers (continued):
Sharing a sentence is not in itself a finding about the gene and the disease.
lung cancer (continued). "However, in lung cancer, miRNA-205-5p was upregulated in tumor tissues and promoted cell proliferation and survival through modulating erbB3." (PMID 35669244, 2022). "Moreover, the suppression of ERBB3-AKT-driven lung cancer spreading requires both kinase-dependent and independent functions of ARAF." (PMID 35938171, 2022). "In addition to KRAS and EGFR T790 mutations, the expression of oncogenes, including MET, HER2 (ERBB2), and epidermal growth factor receptor 3 (HER3, ERBB3), is associated with drug resistance against EGFR-TKIs and leads to tumor recurrence in lung cancers." (PMID 31619200, 2019). "Similarly, gefitinib resistance in lung cancer was also found to be accompanied by ErbB3/HER3 signalling." (PMID 20670437, 2010). "Evidence from lung cancer, pancreatic cancer, melanoma and head and neck cancer suggest that ErbB3-dependent signalling mechanisms are important for not only disease progression, but also resistance to EGFR-targeted therapies." (PMID 18841159, 2008). "In addition, some studies found that the aberrant expression and activation of MET result in the activation of the ERBB3/PI3K/AKT pathway, which is associated with the resistance of EGFR inhibitors in lung cancer, and this resistance can be reversed by combining MET inhibitors and EGFR inhibitors." (PMID 34761497, 2021). "Indeed, ERBB3 has been ‘relatively underinvestigated’ in lung cancer." (PMID 34274969, 2021). "As ErbB3 is essential for growth of EGFR-mutated lung cancer cells, the ZEB1/miR-200 negative feedback loop might potentially provide a cell context-dependent regulation of ErbB3." (PMID 28587302, 2017). "As depletion of NOTCH1 promotes ERBB3 in cells harbouring various gene mutations, such a NOTCH1–ERBB3 axis may be widely present in lung cancer cells and serve as a common signalling mechanism that regulates the growth of ERBB3-dependent cells, especially EGFR-mutated cells." (PMID 27456471, 2016). "Moreover, ERBB3 expression is inversely correlated with GLIPR1 in 230 lung cancers." (PMID 26988096, 2016). "In lung cancer cell lines expressing ERBB2 and ERBB3, ectopic expression ofCD74-NRG1activates the ERBB3 and PI3K-AKT pathways, resulting in increased colony formation in soft agar." (PMID 38414979, 2024). "The EGF receptor (EGFR) family consists of four transmembrane receptors, which include EGFR (HER1/erbB-1), HER2 (erbB-2/neu), HER3 (erbB-3), and HER4 (erbB-4); and is commonly overexpressed in lung cancer." (PMID 39218855, 2024). "For example, in the anti-EGFR target therapy using gefitinib for lung cancer, MET (receptor of HGF) amplification leads to resistance by activating ERBB3 signaling." (PMID 35625759, 2022). "Not only were we surprised by the different regulatory mechanisms of ARAF with respect to the ERBB3-AKT signaling axis, but also by the observation that ARAF, previously classified more as an oncogene, acts as a tumor suppressor in a subset of lung cancers." (PMID 35938171, 2022). "Rearrangements of MET and the ErbB family RTKs (EGFR, ERBB2, ERBB3, and ERBB4) in lung cancer are less well documented and mostly as case reports." (PMID 36369474, 2022). "In a gefitinib-sensitive lung cancer cell line HCC827, focal amplification of MET was found to stimulate ErbB3 phosphorylation which in turn activated downstream PI3K/Akt signaling axis compensating the inhibitory effect of gefitinib on EGFR." (PMID 29455669, 2018). "The HER family is composed of four members, including EGFR/HER1/ErbB1, HER2/ErbB2, HER3/ErbB3, and HER4/ErbB4, and plays a key role in the pathogenesis of various human solid tumors, including breast, gastric and lung cancers." (PMID 29233126, 2017). "Although PRMT5 and p44 are ubiquitously expressed in all cancer cells, we observed heterogeneous expression of ErbB2, ErbB3, and FGFR3 in lung cancer cells and of some PRMT5/p44-target genes in various cancer cell lines in response to p44 silencing." (PMID 27480244, 2016).
lung cancer (continued). "In contrast, lung cancer samples express high levels of PRMT5, WDR77, ErbB2, ErbB3 and FGFR3 and decreased levels of GLIPR1, Leprel1 and BTG2." (PMID 27480244, 2016). "The co-expression of EGFR and MUC1 was higher in tumor cells than EGFR combined with targets under active drug development for lung cancer such as MET, HER3 (ERBB3) or Trop2 (TACSTD2), suggesting the potential safety advantage of developing therapies targeting EGFR and MUC1." (PMID 39664199, 2024). "In lung cancer cells, a signaling network exists between the same RTK family: EGFR, MET, and ERBB3." (PMID 32070026, 2020). "ERBB3 (alias HER3), a member of the epidermal growth factor receptor family, is expressed in normal bronchial epithelia and has been shown to be overexpressed in several cancers including lung cancer." (PMID 31357969, 2019). "Therefore, to explore the molecular mechanism by which HGF reduces sensitivity to gefitinib in lung cancer harboring wild-type EGFR, we examined the phosphorylation status of MET, EGFR, ErbB3, and the downstream signaling pathways by western blotting." (PMID 26919104, 2016). "Nevertheless, it should be noted that the inhibition of NOTCH1 by γ-secretase inhibitor treatment or by siRNAs also significantly promoted both ERBB3 expression and lung cancer cell growth in the absence of gefitinib." (PMID 27456471, 2016). "NRG1 is up-regulated in several types of cancer including breast cancer, lung cancer, pancreatic cancer, and over-expression of NRG1 may activate downstream signaling pathways such as ERBB3/ERBB2 pathway, leading to the stimulation on cancer cell proliferation, invasion, and drug resistance." (PMID 40959099, 2025). "Similarly, ErbB2 and ErbB3 were not expressed in the benign lung epithelial cells (left top two panels, indicated by black arrows) but highly expressed in lung hyperplasia (left, circled by red lines) and in most lung cancer cells." (PMID 27480244, 2016). "Based on previous studies in lung cancer, PI3K signaling could lead to increase cell proliferation even in the absence of ERBB3." (PMID 34843459, 2021).
melanoma (117 papers, 2008 to 2026). A malignant, usually aggressive tumor composed of atypical, neoplastic melanocytes. "Immuno-histochemical analysis showed high ErbB3 levels of expression in melanoma metastases and its association with disease progression." (PMID 31557826, 2019). "Overexpression and oncogenic activation of ERBB3 have been associated to treatment resistance with RAF/MEK inhibitors in melanoma and thyroid cancer, especially in the specific context of BRAFV600E." (PMID 28469731, 2017). "In this paper we first demonstrate that ErbB3/AKT hyperphosphorylation occurs in BRAF mutated melanoma cell lines following exposure to BRAF and/or MEK inhibitors." (PMID 26208478, 2015). "It has been previously proposed that BRAF mutated cancer cells either of melanoma or of thyroid or of colorectal origin, undergo increased ErbB3 protein expression consequent to transcripional activation." (PMID 26208478, 2015). "SOX10 is known to act as a specifier of neural crest derivatives and directly regulates melanoma associated genes like ERBB3, EDNRB and MITF." (PMID 24799129, 2014). "Immuno-histochemical analysis showed high ErbB3 expression in melanoma metastases and suggested increased ErbB3 expression associated with disease progression." (PMID 22889873, 2012). "We considered that Ebp1, following its interaction with ERBB3, may cause an imbalance in ERBB3 in melanoma, which leads to poor prognosis for patients with high Ebp1 expression." (PMID 35093077, 2022). "The second question we have addressed is whether a combinatorial approach with two different antibodies directed against distinct ErbB3 surface epitopes can better inhibit receptor function in BRAF mutated melanomas." (PMID 26208478, 2015). "The role of ErbB3 in melanoma can also be indirectly inferred from the evidence that driver mutations are found in ErbB4, its preferred heterodimerizing partner in these cells, in a significant percentage of melanomas (approximately 20%)." (PMID 22889873, 2012). "We detected clonal mutations of all types that affected genes known to contribute to melanoma initiation, including hotspot SNVs in Kras and Gnaq, SNVs in frequently mutated sites of Sf3b1 and Tfap2a, homozygous deletion of Cdkn2a, and amplifications of Met, Braf, Mitf, Kras, Cdk4, and Erbb3." (PMID 40950124, 2025). "Therefore, we propose that initial co-treatment of melanoma patients bearing BRAF mutations with an anti-ErbB3 antibody could be a powerful strategy to enhance clinical efficacy of BRAF and MEK inhibitors." (PMID 23890105, 2013). "In particular, ERBB3 is overexpressed in advanced melanoma and contributes to drug resistance and EMT-like phenotypes." (PMID 40725203, 2025). "In melanoma, ERBB3 protects cells from ferroptosis by preserving antioxidant defenses, and its inhibition re-sensitizes resistant cells to RSL3 or Erastin treatment." (PMID 40846695, 2025). "Future studies are warranted to test neratinib reversal of BRAFi/MEKi resistance in patient melanomas expressing ERBB3/HER3 in combination with its dimerization partner ERBB2/HER2." (PMID 38854737, 2024). "Despite ERBB3 being identified as a marker of poor prognosis in melanoma and enriched in volar melanocyte transcriptomes, no antitumoral activity was identified with the HER2 inhibitor Lapatinib." (PMID 39627834, 2024). "Four patients diagnosed with ovarian cancer, melanoma, sarcoma, or cholangiocarcinoma received afatinib based on an EGFR or ERBB3 mutation." (PMID 37175010, 2023). "ERBB3 expression has been discovered to be upregulated in numerous types of tumors, including but not limited to breast, ovarian, lung, colon, pancreatic, melanoma, gastric, head and neck, and prostate cancers." (PMID 38144565, 2023). "The loss of LRIG1 in A375 melanoma cells resulted in decreased expression of ERBB receptors upon EGF stimulation and decreased activation of ERBB3." (PMID 33786987, 2021).
melanoma (continued). "FOXD3 is then able to directly activate the expression of ERBB3 at the transcriptional level, enhancing the responsiveness of melanoma cells to NRG1 (the ligand for ERBB3), and thus leading to the reactivation of both MAPK and PI3K/AKT pathways." (PMID 33507915, 2021). "It has been indicated that epidermal growth factor receptors (ERBB) participate in the acquisition of resistance to BRAFi, and the level of ERBB3 protein is increased in resistant melanoma cells." (PMID 33430277, 2021). "ERBB3 plays an important role during melanoma development and contributes to poor survival of melanoma patients with metastases." (PMID 33786987, 2021). "A review mentioned that Notch and ERBB signaling components (i.e., Notch1, Hey1, and ERBB3) are re-expressed in melanoma in a correlative manner, and proposed that the tumorigenesis and development of melanoma require two cascade functions." (PMID 34729100, 2021). "Under the influence of CM derived from NRG1-depleted fibroblasts, melanoma cells exhibited an increase in ERBB3 signaling at a much lower level compared to the control." (PMID 33430277, 2021). "Expression of the transcription factor, forkhead box D3 (FOXD3), in human melanoma cell lines, is induced during blockage of the BRAF/MEK/ERK pathway leading to upregulation of ERBB3 and activation of Akt signaling, which promotes melanoma progression." (PMID 34067095, 2021). "The use of ErbB3/ErbB2 antibodies restores the cytotoxic activity of these drugs in BRAF-mutant melanoma cell lines." (PMID 33036192, 2020). "The results show a strong phosphorylation of ErbB3 in melanoma cells upon treatment with CM from BRAF inhibitor-exposed melanoma cells, similar to what happens after direct cell exposure to the same BRAF inhibitor." (PMID 31557826, 2019). "The results, albeit obtained from a small number (n = 11) of patients, show a statistically significant increase of ErbB3 specific phosphorylation in circulating melanoma cells." (PMID 31557826, 2019). "Our work completes an ERK/SOX10/FOXD3/ERBB3 pathway that governs the FOXD3-mediated adaptive resistance to RAF/MEK inhibitors in mutant BRAF melanoma." (PMID 29295999, 2018). "We have shown that lapatinib inhibits ERBB3 signaling and hampers melanoma cell survival and tumorigenesis." (PMID 28060735, 2017). "In confirmation of that and other studies, we also found low levels of HGF and consistently high levels of MET and ERBB3 RNA in the four melanoma cell lines used in this study (Figure 5a1)." (PMID 28223541, 2017). "Overall these data indicate a combination involving the natural compound fucoidan and ERBB3 inhibition is a promising novel and safe approach in melanoma therapy." (PMID 28060735, 2017). "We have recently shown that melanomas express high levels of ERBB3 and depend on its function for growth and survival." (PMID 28060735, 2017). "We compared basal mRNA expression levels of SOX10, MITF, FOXD3, and ERBB3 in immortalized melanocytes, and in a panel of melanomas spanning various genetic backgrounds." (PMID 27391157, 2016). "Hyper-activation of the PI3K/AKT pathway due to increased NRG1-beta/ERBB3 pathway signaling has previously been reported to be responsible for acquired drug resistance in BRAFV600 melanomas." (PMID 27391157, 2016). "Our data showed the capability of the anti ErbB3 antibodies mAbs to partially inhibit melanoma cells growth also in vivo." (PMID 26208478, 2015). "We have been the first to show that activation of the ErbB3/AKT axis in melanoma can be inhibited by co-treatment with anti-ErbB3 mAbs and that these antibodies synergize with BRAF and MEK inhibitors in short term in vitro clonogenic assays." (PMID 26208478, 2015). "Enhanced ERBB3 signaling promoted resistance to RAF pathway inhibitors in cultured melanoma cell lines and in mouse xenograft models." (PMID 24743024, 2014).
melanoma (continued). "The mechanism of ERBB3 was traced to an autocrine loop that resulted in production of high levels of neuregulin by melanoma cells in response to MAPK pathway inhibition." (PMID 24743024, 2014). "The results of our study show that melanoma cells display a unique composition of cell surface antigens, including ErbB3, IGF-1-R, CD44 and ICAM-1." (PMID 24489649, 2014). "The few targets we were able to detect on melanoma cells were ErbB3, CD33 and CD44, confirming previous observations." (PMID 24489649, 2014). "We have recently shown that melanoma cells often express ErbB3 in concert with other ErbBs and that neuregulin, acting through ErbB3, activates the PI3K/AKT pathway, thus leading to increased cell survival, proliferation and migration." (PMID 23890105, 2013). "We show that upregulation of phospho-ErbB3 is due to an autocrine loop involving increased transcription and production of neuregulin by melanoma cells." (PMID 23890105, 2013). "Surprisingly, we found that in the three melanoma cell lines tested, the only receptor which underwent prominent hyperphosphorylation was ErbB3." (PMID 23890105, 2013). "ErbB3 is frequently expressed in human melanoma cell lines and microarray analysis revealed that ErbB3 was one of a small number of genes whose upregulation is characteristic of melanoma." (PMID 22889873, 2012). "Studies have shown that SOX10 contributes to melanoma’s adaptive resistance to RAF inhibitors via the ERK1/2/SOX10/FOXD3/ERBB3 signaling pathway.The imperative for developing a prognostic model based on SOX10 is to enhance melanoma patients’ survival rates and refine treatment strategies." (PMID 40342816, 2025). "Moreover, the high expression level of ERBB3 significantly correlated with the poor survival rate of melanoma patients." (PMID 35093077, 2022). "Notably, pharmacological BRAF inhibition further stimulated ERBB3 signaling in YAP1-activated melanoma cells in line with a previous report, highlighting ERBB3 as a particularly relevant target in MAPKi-resistant melanoma cells with high YAP1 activity." (PMID 35798875, 2022). "Therefore, we depleted LRIG1 in human melanoma cells (A375) by CRISPR/Cas9 technology and found that this caused EGFR and ERBB3 downregulation in A375 LRIG1 knockout cells 6 h following stimulation with EGF." (PMID 33786987, 2021). "In human melanocytes, MAPK signaling causes reduction of MITF and increases ERBB3, FOXD3 and NRG1 transcription factor gene expression, with NRG1 and FOXD3 also further upregulating ERBB3, which can heterodimerize with EGFR causing melanoma metastasis." (PMID 34067095, 2021). "The potency of these MMAF-based ADCs was confirmed on melanoma cells that overexpress the receptor tyrosine-protein kinase erbB-3, which is also known as HER3 (HER3 allows the escape of tumor cells from vemurafenib-targeted treatment of BRAF-positive melanoma cells)." (PMID 32899183, 2020). "Knockdown of ERBB3 in melanoma can reduce tumor cell migration and invasion." (PMID 32206115, 2020). "However, AXL has been shown to have a dual regulatory function on melanoma cell invasion, given that both inhibition or overexpression enhance invadopodia formation and activity, due to compensatory mechanisms by ERBB3 signaling pathway." (PMID 33203881, 2020). "Interestingly the kinetic of neuregulin production and of the ensuing ErbB3 phosphorylation is different in different melanoma cell lines which underscores the high degree of tumor heterogeneity." (PMID 31557826, 2019). "Although different mechanisms have been invoked in the past at the basis of this activation we show here with a combination of approaches that autocrine production of neuregulin by melanoma cells is a major factor responsible for ErbB3 phosphorylation and downstream AKT activation." (PMID 31557826, 2019).